AVP (arginine vasopressin)
Diseases named in the same sentence as AVP in open-access papers (continued):
Sharing a sentence is not in itself a finding about the gene and the disease.
depression (67 papers, 2007 to 2026). "Stress-induced imbalances in the OT/AVP system have been shown to increase the risk of various mental disorders, including depression, schizophrenia, and autism." (PMID 40437391, 2025). "Our data further support a potential mechanism by which AVP is attenuated by 5-HT, thereby decreasing preeclampsia risk in the setting of poorly controlled, severe depression." (PMID 35984571, 2023). "The objective of the present study was to investigate the associations among AVP secretion, depression symptoms, SSRIs, and preeclampsia during pregnancy to reveal the molecular basis for clinical depression-PreE links." (PMID 35984571, 2023). "AVP has a role in the regulation of hydration, blood pressure, body temperature, corticotropin release, and has been implicated in depression, memory, social and sociosexual behavior and in sex differences." (PMID 33472866, 2021). "Autism spectrum disorder (ASD), Williams syndrome, schizophrenia, depression, social anxiety, and attachment disorders all respond to AVP receptor blockade or seem linked to AVP and OT." (PMID 33477721, 2021). "Enhanced AVP mRNA production leads to increased plasma levels of AVP that have been related to an enhanced suicide risk in depression, as well as to an anxious-retarded type of depression, psychomotor retardation and memory disturbances in depression." (PMID 24318124, 2014). "We further find that decreased AVP secretion with SSRI therapy may decrease preeclampsia risk in those with poorly controlled depression." (PMID 35984571, 2023). "In addition, higher AVP plasma levels in MDD have been associated with distinct depression features, such as melancholic symptoms and psychomotor retardation during the day." (PMID 32508691, 2020). "Central 5-HT activity is linked to changes in AVP, and may also be useful tool for treating deficient maternal behavior due its well-established role in depression." (PMID 22942878, 2012). "There are indications that ELS may alter AVP characteristics in humans as well, and that these may interact with adult predisposition to psychopathology with social dysfunction, such as autism, schizophrenia, depression and personality disorders." (PMID 34502322, 2021). "Depression-related arginine vasopressin (AVP) reduces AHI1 expression, which disrupts Tyk2 and interferon signaling, further compromising immune defense." (PMID 40242760, 2025). "Our findings are consistent with prior reports that AVP mRNA expression is up-regulated in PVN neurons of rats exposed to stress-induced depression models." (PMID 40370500, 2025). "Overall, these findings imply that AVP is a crucial factor in the development and manifestation of depressive behaviors across diverse depression models." (PMID 40370500, 2025). "In particular, increased plasma levels of arginine-vasopressin have been found in patients affected by depression and depressive mood is very common in PCOS patients." (PMID 38485896, 2024). "In pregnant women with depression symptoms, we found here that circulating AVP secretion is elevated." (PMID 35984571, 2023). "Depression elevates arginine vasopressin (AVP), which decreases AHI1 and Tyk2, thus, inhibiting IFN signaling and eventually attenuating the host’s antiviral innate immunity." (PMID 36829909, 2023). "Taken together, these data indicate that AVP dysregulation is a common link between the pathogenesis of PreE and depression." (PMID 35984571, 2023). "The HPA axis is found to be more active in subjects diagnosed with major depressive disorder, which implies a higher rate of synthesis and release of AVP, driving the axis in such cases instead of CRH." (PMID 36829752, 2023). "The purpose of this study was to investigate the relationship between the plasma concentrations of AVP and the score of Edinburgh Postnatal Depression Scale (EPDS)." (PMID 36864065, 2023). "Other groups have demonstrated that AVP is elevated and is important in the etiology of major depressive disorder." (PMID 35984571, 2023).
depression (continued). "Arginine vasopressin (AVP) has been suggested as a hormonal agent involved in the development of depression." (PMID 36864065, 2023). "The data support the delimitation of a largely familial depression with above-normal plasma AVP, vasopressinergic activation of the HPA axis, and a variable anxious-retarded phenotype." (PMID 36004833, 2022). "AVP was also observed as a major factor to regulate depression, especially in two hypothalamic structures SON and PVN which produced plasma vasopressin." (PMID 34717666, 2021). "Earlier work has shown that AVP released by neurons of the SCN strongly affects the depressive disorder among patients." (PMID 34504149, 2021). "Meanwhile, both the AVP and CRH released by the HPA-axis contribute to the signs and symptoms of depression; thus, detecting the hormone concentrations of AVP, CRH and ACTH will be one of our future studies." (PMID 29487521, 2018). "In our previous studies, we found a disturbance in the key output neuropeptide of the SCN, arginine vasopressin (AVP), in depression." (PMID 28608287, 2017). "Zhou and colleagues found increased AVP-immunoreactive cells, but decreased AVP mRNA in the SCN of subjects with depression or bipolar disorder relative to controls." (PMID 29230328, 2017). "Taken together, our findings indicate a reduced stimulatory output from the SCN, i.e., there were more inhibitory GABAergic signaling and less excitatory AVP signaling from the SCN to the projection areas in depression, especially in female patients." (PMID 28608287, 2017). "Previous studies found that Jia-Wei-Xiao-Yao-San ameliorated depression in menopausal women through increasing serum TNF-α and Dang-Gui-Shao-Yao-San improved depression-like behaviors in murine model through decreasing central arginine vasopressin." (PMID 28851349, 2017). "One of the first molecular connections between ELS and depression was established through the arginine vasopressin gene (Avp)." (PMID 27213019, 2016). "In depression, this peptide is overproduced in the hypothalamus, which, acting along with arginine vasopressin (AVP), triggers hypersecretion of adrenocorticotrophic hormone (ACTH) from the pituitary." (PMID 25767450, 2015). "In patients suffering with depression, both plasma levels of AVP and levels of AVP in the paraventricular nucleus are significantly increased." (PMID 25853137, 2015). "Thereafter, we found support for a subcategory of depression with above-normal plasma arginine-vasopressin (ANA) concentration." (PMID 22203891, 2011). "In this context, interest has mainly focussed on the brain neuropeptides corticotrophin releasing hormone (CRH) and vasopressin (AVP), which both exert anxiogenic and depression-like effects." (PMID 27713275, 2010). "Additionally, patients with major depressive disorder (MDD) have a substantial increase in AVP neurons and V1b receptors." (PMID 36829752, 2023). "As a result of this study, we hypothesize that elevated AVP is a molecular link between depression and preeclampsia and indicates a potential therapeutic pathway to target." (PMID 35984571, 2023). "SSRIs may modulate preeclampsia risk and mechanisms, although further studies are needed to investigate the relationships between 5-HT and AVP in depression and preeclampsia." (PMID 35984571, 2023). "Additional findings in animal models also demonstrate cross-talk between vasopressin and serotonin systems at the behavioral level, with V1b receptor antagonism achieving anti-depressant-like effects and SSRI rescue of depression-like phenotypes acting in an AVP-dependent fashion." (PMID 35984571, 2023). "Depression, impulsivity, and violence seem causally linked to AVP regardless of other factors, e.g., sex, stressors." (PMID 33477721, 2021). "Indeed, our group has observed lower levels of AVP-mRNA together with higher levels of AVP-ir in depression in a previous study." (PMID 28608287, 2017). "AVP is involved in the pathogenesis of depression by regulating the HPA axis function." (PMID 27413389, 2016).
depression (continued). "Also plasma arginine vasopressin increase in depression was inversely related to daytime motor activity." (PMID 17868435, 2007). "Additionally, BPF exhibits antidepressant effects by reducing levels of arginine vasopressin in the pituitary, decreasing the expression of arginine vasopressin mRNA in the hypothalamus and increasing plasma tumor necrosis factor-α levels in menopausal patients with depression." (PMID 38921335, 2024). "AVP may also be a potential biomarker for the efficacy of depression treatment efficacy." (PMID 35984571, 2023). "Therefore, shifting neuropeptide homeostasis to OXT by suppressing brain AVP may be beneficial in the treatment of depression." (PMID 36430254, 2022). "Similarly, rodent models of autism and depression frequently report changes in AVP and OXT systems." (PMID 31404254, 2019). "In addition, the functional consequences of the significantly increased SCN AVP-ir in female depression patients for SCN function and its output may be related to the higher vulnerability for depression in women." (PMID 28608287, 2017). "For example, early life stress resulted in hypomethylation of an enhancer that regulated arginine vasopressin (AVP) expression in mice, and hypomethylation of this AVP enhancer increased its activity, thus increasing expression of AVP in the PVN, an expression profile associated with depression." (PMID 23265842, 2013). "Post-mortem examinations of human brains revealed the elevated expression of AVP mRNA in the PVN and SON and a significantly greater number of AVP and OT neurons in the PVN of patients with MDD (major depressive disorder)." (PMID 35207180, 2022). "The neuropeptides, CRF and AVP, are released within the paraventricular nucleus (PVN) of the hypothalamus and are crucially involved in the pathogenesis of depression." (PMID 29487521, 2018). "In this study, the number of cells that was AVP and/or VIP-immunoreactive was increased in the SCN of individuals with major depression or bipolar disorder." (PMID 29230328, 2017). "There are currently many clinical trials exploring the therapeutic value of OT and AVP (e.g., in ASD, schizophrenia, major depressive disorder, and substance dependence)." (PMID 27920663, 2016). "Since also early types of stress can epigenetically program the AVP gene in a long-lasting manner, the AVP-driven HPA axis hyperactivity in depression is receiving more attention." (PMID 24318124, 2014). "Fourth, AVP is released into the brain with a circadian rhythm by neurons of the biological clock or SCN, which shows significant changes in depression." (PMID 24318124, 2014). "Thus, whereas CRF and AVP with their described anxiogenic and depression-like effects could represent Scylla and Charybdis in behaviour regulation, OXT like Circe counteracts these effects and mediates anxiolysis, calmness, rewarding and the positive consequences of social support." (PMID 27713275, 2010). "One potential mechanism may involve arginine vasopressin (AVP) which affects stress, vascular, immune, and osmotic responses in the body and plays a role in depression symptoms." (PMID 35984571, 2023). "As a marker of AVP secretion, we demonstrate that maternal plasma copeptin at less than 20 weeks of gestation was higher in women with moderate-to-severe depression symptoms in comparison to those with no-to-mild symptoms." (PMID 35984571, 2023). "A few previous studies on the relationship between AVP and depression in non-pregnant populations are as follows." (PMID 36864065, 2023). "On the contrary, a Brattleboro rat lacking AVP was less anxious and showed reduced depression-like behavior accompanied by changes in HPA axis regulation." (PMID 34502322, 2021). "In the group of people with depression, an increased concentration of corticotropin releasing factor (CRF) in the cerebrospinal fluid and an increase in the secretion of the hypothalamic neurohormone arginine vasopressin (AVP) were both observed." (PMID 34685427, 2021).
depression (continued). "It should also be noted that the hyperactivity of the HPA axis in depression may contribute to the disturbance of the SCN, since we observed that glucocorticoids show an inhibitory effect on AVP mRNA expression in the human SCN." (PMID 28608287, 2017). "The regulatory effect of AVP on the hypothalamic-pituitary-adrenal (HPA) axis suggests that AVP receptor (AVPR) modulators could be used to treat various central nervous system disorders, including depression, anxiety, and post-traumatic stress disorder." (PMID 40437391, 2025). "The increased SCN AVP-ir in female—but not in male-depression patients—may reflect the higher vulnerability for depression in women." (PMID 28608287, 2017). "In addition, there were a significant 253% increase of AVP-ir in female depression subjects but not in male depression patients." (PMID 28608287, 2017). "One study evaluating the pituitary response to CRF stimulation in women with/without an episode of major depression and/or with a history of sexual abuse with assessment of CRF and AVP concentrations in CSF showed nearly 60% variability in the ACTH response to CRF stimulation." (PMID 34685427, 2021).
heart failure (66 papers, 2006 to 2025). Inability of the heart to pump blood at an adequate rate to meet tissue metabolic requirements. "The levels of AVP have been found to rise progressively with increasing New York Heart Association (NYHA) class of heart failure." (PMID 41179034, 2025). "Apart from its function as a neuroendocrine messenger, AVP is associated with the progression of myocardial remodeling and the facilitation of water-sodium retention in the early stages of heart failure." (PMID 40161384, 2025). "AVP is a key player in the neurohormonal mechanisms underlying heart failure, contributing to fluid retention and vascular resistance." (PMID 41179034, 2025). "In patients with heart failure, decreases in effective circulatory blood volume paradoxically cause AVP increase." (PMID 35327416, 2022). "While AVP can protect the heart from myocardial injuries, high levels of circulating AVP and V1aR overexpression have been associated with heart failure, indicating the importance of V1aR signaling strength." (PMID 33477721, 2021). "Impaired renal water excretion is closely associated with an exaggerated release of AVP in heart failure." (PMID 26239456, 2015). "This is partly based upon the findings that arginine vasopressin is one of the hormones stimulated during the activation of multiple neurohumoral systems that occurs in association with progression of the heart failure." (PMID 16737547, 2006). "The use of SGLT2 inhibitors in patients with heart failure is associated with an increase in the co-peptin level, a marker for AVP release, which promotes water conservation in the setting of the osmotic diuretic effect of glycosuria and prevents a significant increase in urine volume." (PMID 40217758, 2025). "The inhibition of the translocation of AQP2 into the plasma membrane may be an approach to reduce edema in heart failure where elevated levels of AVP cause a predominant localization of AQP2 in the plasma membrane of the renal principal cells." (PMID 35054947, 2022). "Moreover, experimental data revealed that heart failure is associated with significant changes of AVP content in cardiovascular brain regions." (PMID 34768894, 2021). "Under normal circumstances, AVP release is regulated by plasma osmolality; however, in heart failure, its release is predominantly driven by baroreceptors sensing reduced effective arterial volume." (PMID 41179034, 2025). "While it initially acts to preserve circulatory function in the setting of reduced cardiac output, chronic elevation of AVP has adverse effects that exacerbate heart failure." (PMID 41179034, 2025). "In heart failure, copeptin reflects the activation of the arginine vasopressin (AVP) system, a response to decreased cardiac output and other stressors." (PMID 40244022, 2025). "Since AVP levels are elevated in heart failure, the vasopressin receptor blockade was studied as a target for therapy." (PMID 40217758, 2025). "Elevated levels of AVP in heart failure are considered to be a factor in the advancement of left ventricular remodeling by promoting the hypertrophy of cardiomyocytes." (PMID 39597026, 2024). "In cases of heart failure (HF), the secretion of AVP increases in response to a reduced blood volume and decreased cardiac output." (PMID 39432214, 2024). "Elevated AVP has been shown to be a marker of poor prognosis in the heart failure population and can be a potential prognostic biomarker." (PMID 37508636, 2023). "In a normal physiologic state, AVP elevation does not have significant hemodynamic effects, whereas, in patients with heart failure, AVP elevation can have significant effects on hemodynamics and ventricular function." (PMID 37508636, 2023). "A rodent study for example showed that AVP plasma values increased in male and female rats with heart failure whereas mRNA levels were lower in females than in males." (PMID 36434506, 2022).